SMCO1 (single-pass membrane protein with coiled-coil domains 1)
Synonyms: C3orf43; FLJ41923; DKFZp313B0440
Tractability: Antibody: UniProt predicts a signal peptide or a membrane-spanning region.
Gene: Protein-coding gene on chromosome 3 (196,506,878 to 196,515,347, reverse strand). Ensembl gene ENSG00000214097.
Subcellular location: Membrane
Subcellular location (Human Protein Atlas): Golgi apparatus; Endoplasmic reticulum
Gene Ontology:
Molecular function: protein binding
Cellular component: membrane
Genetic constraint (gnomAD): Loss-of-function variants: 8 observed, 9.37 expected, observed/expected ratio (o/e) 0.85, 90% interval 0.5 to 1.52. That is too few expected variants to judge how well the gene tolerates losing a copy. Missense variants: 207 observed, 253.95 expected, observed/expected ratio (o/e) 0.82, 90% interval 0.73 to 0.92. Synonymous variants: 85 observed, 91.99 expected, observed/expected ratio (o/e) 0.92, 90% interval 0.77 to 1.11.
Homologues: Orthologues: chimpanzee SMCO1 (98% identical), pig SMCO1 (85% identical), dog SMCO1 (84% identical), rabbit SMCO1 (84% identical), rat Smco1 (77% identical), mouse Smco1 (76% identical), guinea pig SMCO1 (72% identical), tropical clawed frog smco1 (26% identical).
Diseases named in the same sentence as SMCO1 in open-access papers:
SMCO1 is named in the same sentence as 2 diseases in open-access papers, as found by Europe PMC text mining. Sharing a sentence is not in itself a finding about the gene and the disease. The quoted sentences say what the papers report.
breast carcinoma (1 paper, 2019). "However, we have not found any research on SMCO1 in breast cancer; we speculate that it may also play an important role in breast cell proliferation." (PMID 31297036, 2019).
glioma (1 paper, 2021). A benign or malignant brain and spinal cord tumor that arises from glial cells (astrocytes, oligodendrocytes, ependymal cells). "Further experimental studies are needed to validate our conclusions and explore the specific function of SMCO1 in glioma." (PMID 34869577, 2021). "The functional analyses indicate that SMCO1 might play an important role in the glioma microenvironment, thereby influencing the development and progression of glioma." (PMID 34869577, 2021).